TGFBR2 (transforming growth factor beta receptor 2)
Diseases named in the same sentence as TGFBR2 in open-access papers (continued):
Sharing a sentence is not in itself a finding about the gene and the disease.
tumor (443 papers, 1999 to 2026). "ARID1A has been previously reported to maintain acinar homeostasis and prevent PDAC transformation in engineered mouse models, while loss of TGFBR2 contributes to tumor development mainly through the TGF-β signaling pathway." (PMID 41480763, 2026). "Tgfbr2 deficiency in lung epithelial cells (EPs) induces the transformation of non‐invasive Kras mutant tumours to an invasive form." (PMID 41431249, 2025). "Conversely, in TLS-deficient microenvironments, the relationship between GDF15 and TGFBR2 is associated with tumour invasion and subsequent metastasis." (PMID 39901202, 2025). "Loss or reduced expression of TGFBR2 has been implicated in promoting tumor development and progression." (PMID 40978038, 2025). "For the single slide Perturb-map dataset, the perturbation (Jak2-KO, Tgfbr2-KO, Ifgbr2-KO, or control) and spot type (tumor, normal, or periphery) are encoded in the perturbation module." (PMID 41292874, 2025). "As a key receptor in TGF-beta signaling, TGFBR2 loss-of-function mutations can shift TGF-beta from a tumor-suppressive to a pro-oncogenic role, promoting immune evasion and metastasis." (PMID 40282485, 2025). "Tumour cells simulating the Kras mutation Tgfbr2 deletion in vitro were able to highly express and hyper‐secrete TGFβ1." (PMID 41431249, 2025). "And we found T cells were enriched in junction areas of TMPT tumor and normal tissues, but excluded in intratumor regions, suggesting Tgfbr2 loss promoted immune evasion through excluding T lymphocytes infiltration." (PMID 39049720, 2024). "The clinical tumor grade and tumor stage of PC patients were all positively linked with high TGFBR2 expression levels." (PMID 37844011, 2023). "Our results showed that USP33 deficiency significantly decreased the tumor growth of subcutaneous xenograft nude mice while the overexpression of TGFBR2 rescued the effect of USP33." (PMID 37322017, 2023). "Deficiencies due to mutations in TGFBR2 gene function are associated with Marfan syndrome, Loeys–Deitz aortic aneurysm syndrome, and tumor progression." (PMID 37509254, 2023). "As a result, it leads to epigenetic silencing of gene expressions and subsequently, the inactivation of the relevant gene (i.e., MLH1) followed by mutation of tumor suppression genes encoding tumor-suppression proteins (i.e., TGFBR2 and BAX)." (PMID 35883434, 2022). "(see Section 3), PanIN progression mechanisms involve mutations in tumor-suppressing genes that lead to the activation of TGFβ signaling pathways (SMAD4/TGFBR1/TGFBR2)." (PMID 35565450, 2022). "Along with the diverse molecular functions enriched for MSI events in these tumor types, some genes (TGFBR2, ACVR2A, and BAX) are particularly susceptible in MSI-H CRCs, and BAX is also susceptible in MSI-H gastric cancers." (PMID 36531239, 2022). "For instance, TGFβ has been shown to be potently tumour suppressive in disease initiation as illustrated by the frequent mutations to signalling components, TGFβ-receptor-2 (TGFBR2), TGFBR1 and SMAD4 in human PDAC." (PMID 34638468, 2021). "Regions that encode gene products (proteins) involved in tumor suppression (e.g., TGFBR2), cellular growth, DNA repair (e.g., MSH3, MSH6), and apoptosis (e.g., BAX) contain repeat sequences, and genetic changes are likely to occur in these regions." (PMID 34185173, 2021). "In the present study, we showed that fibrotic niche generation was significantly suppressed in Tgfbr2 knockout mouse liver, which was associated with reduced tumor growth." (PMID 33558489, 2021). "Epithelial depletion of the type 1 receptor promoted pancreatic tumourigenesis, in line with findings in Smad4 and Tgfbr2 deficient models, however, systemic depletion revealed important TGFβ-mediated control of the tumour microenvironment (TME)." (PMID 34638468, 2021).
tumor (continued). "The association between TGFBR2 low expression and high tumor grade tumor was reported in other studies." (PMID 34571856, 2021). "Initial studies in mice with Tgfbr2-deficiency in myeloid cells showed reduced tumor growth, which was associated with an increased anti-tumor polarization of macrophages." (PMID 34868988, 2021). "Immunohistochemical analysis demonstrated that 2G8 stimulated cancer cell proliferation in wild‐type tumors but reduced tumor cell proliferation in Tgfbr2‐deficient tumors." (PMID 31609088, 2019). "TGFBR2 deficiency in colon epithelial cells is considered to drive MSI tumor progression by abrogating downstream Transforming Growth Factor-beta (TGF-β) signaling." (PMID 31454892, 2019). "In CMS1 CRC, MSI-H provides accumulation of many somatic gene mutations including TGFBR2, which results in the release of tumor neoantigens and activation of tumor immunity." (PMID 31756952, 2019). "In previous work, we have shown that the recurrent MSI tumor driver mutation affecting TGFBR2 can modulate the cargo of MSI tumor cell-derived EVs at a qualitative level." (PMID 31454892, 2019). "We found that in the control tumors, 2G8 significantly increased tumor growth, but 2G8 significantly slowed the growth of Tgfbr2‐deficient tumors." (PMID 31609088, 2019). "Although high immune response in MSI-H CRC is the result of tumor neoantigen load caused by hypermutation, TGFBR2 impairment can also directly promote inflammation in the tumor microenvironment of CRC." (PMID 31756952, 2019). "Orthotopic injection of 200–106 CD34+ cells from Tgfbr2 cKO anorectal SCC into recipient Nu/Nu mice caused secondary tumor formation with 100% efficiency (n = 89)." (PMID 28219480, 2017). "In this study, we used the murine Tgfbr2-deficient anorectal SCC model to study the consequences of loss of TGFβ signaling in CSC-driven tumor propagation and metastasis." (PMID 28219480, 2017). "We found that 59/61 (97%) of MSI tumours had both TGFBR2 and ACVR2A insertion/deletion (indel) mutations in homopolymer regions of the targeted genes." (PMID 27302369, 2016). "It has been demonstrated that loss of TGFBR2, specifically within the stroma, results in enhanced tumor progression." (PMID 27827906, 2016). "Copy number analysis also revealed that loss of heterozygosity occurred in both TGFBR1 and TGFBR2 genes including in tumours with missense mutations in TGFBR2." (PMID 27558455, 2016). "These analyses indicate that potentially damaging mutations in TGFBR1 occur early in 25% of tumours harbouring these mutations and in 42% of tumours harbouring potentially damaging TGFBR2 mutations." (PMID 27558455, 2016). "High TGFB2, TGFB3 and TGFBR2 mRNA levels in tumours were generally associated with better prognosis for patients, especially those diagnosed with lymph node-negative diseases." (PMID 26703884, 2015). "The TGFBR2 gene encodes for a member of the Ser/Thr protein kinase family and has a tumour suppressor or promoter role depending on cellular context." (PMID 26437339, 2015). "In the example, loss of TGFBR2 in mammary epithelial cells or fibroblasts increased tumor formation and enhanced many markers of tumor progression." (PMID 22233831, 2012). "It has been postulated that structural alterations of TGF-β pathway components, such as mutations of TGFBR2 render tumor cells insensitive to TGF-β cytostatic effects." (PMID 21826227, 2011). "In CCRCC, loss of TGFBR2 has been reported, which has been associated with tumor progression and also suggested to be the mechanism responsible for the escape from TGF-β-mediated growth repression." (PMID 21826227, 2011). "Nonetheless, it is unlikely that chemotherapy use substantially differed according to TGFBR2 or BAX mutation status in tumor, since such data were typically unavailable for treatment decision making." (PMID 21949851, 2011).
tumor (continued). "Experiments with a transplanted and spontaneous mammary carcinoma demonstrated increased levels of TGF-β in the tumor microenvironment if the tumor cells were deficient for the type II TGF-β receptor (Tgfbr2 KO)." (PMID 20490273, 2010). "However, in this study, the administered product was monocyte-derived dendritic cells loaded with frameshift-derived neoantigens of TGFBR2 and caspase-5, in addition to tumor-associated peptide carcinoembryonic antigen (CEA)." (PMID 41463230, 2025). "Of note, the TGFBR2 variant in M30 was only detected in one out of four tumor samples." (PMID 41044171, 2025). "On the other hand, Tgfbr2‐deficient tumor cells may also alter the tumor microenvironment by increasing the secretion of fibroblasts‐recruiting factors." (PMID 39049720, 2024). "Loss or downregulation of TGFBR2 expression leads to uncontrolled growth of tumor cells." (PMID 39525474, 2024). "TGFBR2 is an important component of the TGF-β signaling pathway, and loss or reduced expression of TGFBR2 may abrogate TGF-β signaling to promote tumor progression." (PMID 35198889, 2022). "Furthermore, the HCC-associated reduction in TGFBR2 is consistent with loss of the tumor-suppressor function of TGF-β signaling in hepatocytes." (PMID 35677836, 2022). "However, additional work in prostate tissue recombination allografts in the renal capsule revealed that stromal loss of Tgfbr2 in mice can facilitate tumor progression to adenocarcinoma." (PMID 36671452, 2022). "Three of these six patients with TGFBR2 germline mutations had the same second‐hit mutation in TGFBR2 (c.382_383delAA) in their tumors and these patients had similar clinicopathological features, including proximal tumor locations, early TNM stages and the EMAST(+)‐MSI‐H subtype." (PMID 31769227, 2020). "In addition, EC-specific TGFbR2 deletion in the tumor is associated with increased tumor regrowth after radiation therapy because of enhanced TGFβR1 signaling." (PMID 32467609, 2020). "It was found that loss of one TGFBR2 allele is associated with tumor progression and metastasis." (PMID 30863498, 2019). "Moreover, TGFBR2 disruption in combination with inflammation in the colon causes invasive CRC via tumor-associated macrophage (TAM) infiltration." (PMID 31756952, 2019). "It is worth noting that TGFBR2 is located at chromosome 3p, a region with the most frequent loss of heterozygosity in NPC, implying that TGFBR2 might be a tumour suppressor gene that is altered in the early stages of NPC pathogenesis." (PMID 30060514, 2018). "Thus deletion of Tgfbr2 in the context of a tumor initiating mutation results in an increase in the basal cell population together with a rapid transition to invasive cancer." (PMID 29782499, 2018). "Indeed, components of the TGFβ pathway such as SMAD4 and the ligand receptor TGFBR2 are encoded by classic tumour suppressor genes, which undergo direct loss-of-function mutation during tumorigenesis in certain cancers." (PMID 29146913, 2017). "Similarly, other studies in a mouse mammary tumor virus driven Polyoma Virus middle T antigen (MMTV–PyVmT) tumor model have shown that loss of one Tgfbr2 allele in fibroblasts can induce early tumor onset and increased metastasis." (PMID 28098775, 2017). "Moreover, we uncovered that a recurrent MSI tumor driver mutation like TGFBR2 can reprogram the protein content of MSI cell-derived exosomes and in turn modulate the cytokine secretion profile of recipient cells." (PMID 28376875, 2017). "We reasoned that deletion of Tgfbr2 may cause a decrease of K14+ cancer stem cells population, which subsequently impaired the invasive capability of tumor." (PMID 27378170, 2016).
tumor (continued). "Subsequent functional analysis of four TGFBR1 mutants and five TGFBR2 mutants indicated that half of the TGFBR1 mutants and all five TGFBR2 mutants were loss of function for canonical Smad signalling, and that tumours harbouring TGFβ receptor mutations had reduced PO4-SMAD3 activity." (PMID 27558455, 2016). "The mechanisms underlying the reduced TGFBR2 expression in tumours and the differentially regulated TGFB1 and TGFB3 expression by malignant and premalignant tumour cells may also have potential clinical implications that need to be further explored." (PMID 26703884, 2015). "Is has been hypothesized, that TGFBR2 repression is responsible for most of the tumor associated TGFβ1 resistance observed in vivo." (PMID 23951322, 2013). "TGFBR2 and other genes implicated in neoplasia may be targets for regulation by aberrant miRNAs in cancer." (PMID 21401928, 2011). "TGF-β exerted its tumor-suppressor effects on many tumors by binding to the transmembrane TGF-β type II receptor (TGFBR2, a tumor suppressor), which caused the recruitment of the TGF-β type I receptor (TGFBR1) with subsequent activation of the receptor complex." (PMID 18570662, 2008). "However, in the Tgfbr2‐deficient tumors, 2G8 enhanced the survival and reduced tumor weight." (PMID 31609088, 2019). "Thus, our findings indicate that polymorphisms in TGFBR2 may potentially affect inter-individual variation in anti-tumor immune response through FcG receptor modulation." (PMID 27533245, 2016). "Early genetic loss of TGFBR2 may lead to rapid tumor growth." (PMID 25849327, 2015). "Specifically, among all the enriched targets, NF2, ARID1A, and TGFBR2 emerged as the top 3 enriched targets that were identified in more than half of the replicates, highlighting their substantial effect on tumor development." (PMID 41480763, 2026). "The TGF‐B1/TGFBR2 signalling axis mediated tumour‐CD4+ T cell communication, suppressing CD4+ T cell anti‐tumour activity and resulting in reduced CD4+ T cell enrichment and poor prognosis." (PMID 41492119, 2026). "TGFBR2 behaves as an oncogene and TGFBR2 mutations were documented in up to 40% of patients with CRC, leading to chemotherapy resistance and immunosuppression, and consequently promoting tumor angiogenesis." (PMID 41590248, 2026). "Genes involved in tumor suppression (e.g., TGFBR2), cell proliferation, DNA repair (e.g., MSH3, MSH6), and apoptosis (e.g., BAX) contain these repetitive sequences in the coding regions, where alterations tend to develop." (PMID 41214301, 2026). "Some genes containing these repetitive sequences code for proteins involved in tumor suppression (e.g., TGFBR2), cellular proliferation, DNA repair (e.g., MSH3, MSH6), and apoptosis (e.g., BAX)." (PMID 41214301, 2026). "In the tumor microenvironment, persistent activation of TGFBR2 contributes to immune suppression and resistance to immunotherapy." (PMID 41050697, 2025). "In contrast, MEIS1 inhibits TGFBR2 expression probably in both normal pro-B-cells and tumour cells of the corresponding BCP-ALL subtype." (PMID 41153416, 2025). "Early investigations revealed that reduced expression of Tgfbr2 in lung cancer cells promotes cellular invasiveness, indicating its potential role as a trigger in the early stages of tumour development or dissemination." (PMID 41431249, 2025). "These potent anti-tumor effects are concurrent with simultaneous reduction in expression of multiple putative oncogenes downstream of TGFBR2, essentially mimicking a combinatorial treatment strategy, highlighting the translational potential of this approach." (PMID 40301302, 2025). "To test these predictions, we examined the effects of conditioned medium (CM) obtained from mGSCs ± TGFBR2 inhibition on the viability and tumor cell-killing capacity of PBMC-derived CD4+ and CD8+ T cells." (PMID 40277917, 2025). "We discovered that both tumor types also shared an eroded downstream canyon border at TGFBR2, which in EOCRC was more pronounced." (PMID 39844333, 2025).
tumor (continued). "Network analysis uncovered miR-590-3p as a tumor suppressor that simultaneously inhibits multiple oncogenic nodes downstream of TGFBR2." (PMID 40301302, 2025). "Transforming growth factor beta receptor II (TGFBR2), a transmembrane serine-threonine kinase, functions as a tumor suppressor gene, often downregulated in various cancers." (PMID 40936702, 2025). "In contrast, our data in LUAD uncover a TGFβ1‐centric mechanism whereby Tgfbr2‐deficient tumour cells secrete TGFβ1 to induce PLVAP in tip‐like ECs, driving tumour invasiveness." (PMID 41431249, 2025). "CONCERT shifted the NEX profile of the central Tgfbr2-KO patch toward that of the actual tumor-periphery niche: for Fn1, mean NEX decreased from 3.917 to 3.228, approaching the observed value in tumor periphery (2.625)." (PMID 41292874, 2025). "The neoplasm showed high expression levels of LGR5 (stem cell marker gene, investigated as a therapeutic target in CRC), FN1 (extracellular matrix remodeling), and TGFBR2 (conditional tumor suppressor/activator as part of TGF signaling)." (PMID 40667282, 2025). "We selected observed Tgfbr2-KO spots in a normal-like niche and in silico perturbed the surrounding spots to resemble tumor periphery." (PMID 41292874, 2025). "We show miR-590-3p functions as a tumor suppressor that promiscuously blocks multiple SMAD2/3 targets downstream of TGFBR2 in GBM neurospheres." (PMID 40301302, 2025). "We found significantly enhanced PLVAP expression on ECs using human (A549) or mouse LUAD tumour cell lines (LKR Tgfbr2 KO) co‐cultured with HUVEC." (PMID 41431249, 2025). "To verify the functional involvement of TGFBR2 in radiation-induced skin injury, we established an in vitro X-ray irradiation model using HSF." (PMID 41050697, 2025). "First, we analysed 14 226 EPs, which were classified into normal EP, K tumour EP and KT tumour EP according to their origin and the level of expressing Kras and Tgfbr2." (PMID 41431249, 2025). "At present, many studies have confirmed TGFBR2 as an important tumor-suppressive factor, while the mechanism of its effect on BC development remained unclear." (PMID 39525474, 2024). "Together, these data highlight the importance of conventional tumor suppressor genes (e.g., Tsc1 and Tgfbr2) in repressing tumor metastasis and the dynamic nature of clonal persistence and expansion." (PMID 38997291, 2024). "In our study, we found the carcinogenesis effect of miR-301b-3p and the tumor-suppressive effect of TGFBR2 on BC cells." (PMID 39525474, 2024). "Our results revealed a high interaction potential between TGFβ secreted from immune cells and TGFBR1 and TGFBR2 in tumour cells." (PMID 38426403, 2024). "Here, the data revealed a tumor-promoting role of miR-301b-3p and a tumor-suppressive role of TGFBR2 in BC, suggesting that miR-301b-3p can enhance BC development through suppressing TGFBR2." (PMID 39525474, 2024). "For instance, experimental evidence demonstrates that haploid loss of TGFBR1 and TGFBR2 impairs SMAD signaling and promote tumor progression in mouse models." (PMID 38753874, 2024). "Taking together, these results suggested Tgfbr2 loss promoted tumorigenesis of NPC and promoted immune evasion of NPC through concerting tumor microenvironment (TME) to a fibroblasts‐enriched, collagens‐filled, and lymphocytes excluded state." (PMID 39049720, 2024). "The carcinogenic role of tobacco smoke is supported by our observation of DBS2-matching doublet mutations occurring in tumor suppressor genes FBXO11 and TGFBR2 in the samples of two individuals with a smoking history." (PMID 38711096, 2024).